Y_RNA (Y RNA )
Gene: Miscellaneous RNA gene on chromosome 12 (113,156,763 to 113,156,861, reverse strand). Ensembl gene ENSG00000199899.
Homologues: Orthologues: macaque Y_RNA (72% identical), chimpanzee Y_RNA (68% identical). Paralogues in human: Y_RNA (80% identical), Y_RNA (79% identical), RNY3 (78% identical), Y_RNA (78% identical), RNY3P1 (77% identical), Y_RNA (77% identical), Y_RNA (76% identical), RNY3P9 (75% identical), Y_RNA (75% identical), RNY3P14 (74% identical), RNY3P2 (74% identical), RNY3P3 (74% identical), and 89 more.